TFEB (transcription factor EB)
Diseases named in the same sentence as TFEB in open-access papers (continued):
Sharing a sentence is not in itself a finding about the gene and the disease.
tumor (continued). "The tumour cells were also positive for GATA3, E-cadherin, Pax-8, Succinate dehydrogenase B (SDHB) and Fumarate hydratase (FH), and negative for vimentin, Carbonic anhydrase 9 (CA9), CD10, P504s, CK20, TFE3, TFEB, HMB45, ALK and Forkhead box protein I1 (FOXI1)." (PMID 36816543, 2023). "The hypothesis that TFEB and lysosomes are directly involved in the pathogenesis of TSC via a non-canonical RAGC-dependent mechanism challenges the concept that hyperactivity of mTORC1 to its canonical substrates is the unique driver of tumor formation in TSC." (PMID 34253722, 2021). "Therefore, TFEB might regulated MMP2 and MMP9 expression through lysosomal biogenesis in the tumor environment." (PMID 33732651, 2021). "Importantly, TFE3 but not TFEB is essential for the survival of tumour cells." (PMID 33145941, 2020). "Although TFEB was not detectable in SPN (data not shown), TFE3 and MITF were both highly expressed in SPN compared to other tissue types, including tumor and benign tissues (cohorts 1/2)." (PMID 41310888, 2025). "All tumour cells were negative for vimentin, CA9, CD10, P504s, CK20, TFE3, TFEB, HMB45, ALK and FOXI1." (PMID 36816543, 2023). "Furthermore, by LSCM, an increase in TFEB nuclear translocation was clearly observed after MCU was activated, whereas the opposite change was detected in MCU-inhibited cells, suggesting that MCU could activate TFEB-driven autophagy to promote tumor cell migration." (PMID 37885995, 2023). "However, we did not observe significant neddylation modification of TFEB in tumor cells, indicating that UBC12 does not directly regulate TFEB." (PMID 38926803, 2024). "All the five tumours in this study had a typical immunophenotype characterized by diffuse positivity for CK7 and negativity for CD117, and were also positive for PAX-8, E-cadherin, FH and SDHB, but negative for vimentin, CD10, P504s, CA9, CK20, TFE3, TFEB, HMB45, and ALK." (PMID 36816543, 2023). "The tumor is characterized by the fusion of the non-protein-coding gene Alpha (MALAT1) located at 11q12 and the TFEB gene of 6p21, which up-regulates the expression of TFEB, leading to abnormal expression of melanocyte markers, that is just the opposite of NDs in gene regulation." (PMID 35531069, 2022). "Tumor growth was modestly, although non-significantly, suppressed in cells stably expressing FLCNF118D/ FNIP2 consistent with the more attenuated rescue of TFEB phosphorylation in vivo compared to what was observed in vitro, potentially due to issues with long-term expression of these constructs." (PMID 36357396, 2022).
cancer (146 papers, 2010 to 2026). A tumor composed of atypical neoplastic, often pleomorphic cells that invade other tissues. "The addition of BCAAs' catabolic products can reverse the arrest effect caused by TFEB knockdown so that cancer cells can return to the normal cell cycle and resume rapid growth and proliferation." (PMID 38938061, 2024). "The experimental findings indicated that a reduction in TFEB expression was linked to a decline in the ability of cancer cells to resist radiation, implying that the lysosome plays a noteworthy role in autophagy-mediated radioresistance." (PMID 38162504, 2023). "TFEB has recently emerged as a critical player in a wide array of cancer-associated conditions, in which it was found to promote tumorigenesis." (PMID 36888606, 2023). "A noncanonical role for TFEB has also been proposed as important in cancer with the identification of an association between TFEB and renal oncogenesis." (PMID 36794754, 2023). "Given that KEAP1 and NRF2 are frequently mutated in cancer, it will be interesting to explore the involvement of TFEB/TFE3 in NRF2-driven cancers." (PMID 37216554, 2023). "The number of cells undergoing DNA replication was decreased by TFEB knockdown, which was associated with G1/S arrest and the induction of apoptosis in cancer cell lines." (PMID 36372230, 2022). "Taken together, these results indicate that Kazinol C induces ER stress-associated UPR and TFEB activation in both normal and cancer cells." (PMID 35308126, 2022). "Since TFEB knockdown does not cause apoptosis in MCF10A cells, we propose a model wherein TFEB is necessary for cell survival in cancers containing certain oncogenic variations." (PMID 36372230, 2022). "The results revealed that TFEB expression was up-regulated in PCa tissues and was associated with cancer metastasis." (PMID 33732651, 2021). "TFEB levels are elevated in different human cancers and are associated with occurrence and poor prognosis." (PMID 34091590, 2021). "In multiple types of human cancers, the expression and activity of TFEB are elevated and are associated with enhanced motility and proliferation; thus, it was originally described as an oncogene." (PMID 34091590, 2021). "In these human cancers, amplification of TFEB expression is associated with multidrug resistance, aggressive behavior, and poor prognosis." (PMID 34091590, 2021). "Several other studies have also demonstrated that TFEB is associated with the growth, proliferation, migration and metastases of cancer cells." (PMID 33419007, 2021). "Upregulation of MiT/TFE factors has been implicated in various cancers, and a recent study documented that upregulation of TFEB contributes to increased autophagy in PDAC." (PMID 27626694, 2016). "In addition to the finding that TFEB plays a pathogenic role in several cancers, TFEB plays a protective role in most diseases, such as LSDs, neurodegenerative diseases, ischemic injury, metabolic disorders, and inflammation." (PMID 38365838, 2024). "Our results suggest that lactylation is a novel mode of TFEB regulation and that lactylation of TFEB may be associated with high levels of autophagy in rapidly proliferating cells, such as cancer cells." (PMID 39196068, 2024). "Predisposed to genomic instability, nutritional, and oxidative stress in a stage‐dependent manner, cancer cell formation (tumorigenesis) and subsequent survival provide a paradigm for understanding the diverse pathogenic roles of TFEB‐induced upregulation of the ATGs and other CLEAR network genes." (PMID 37728021, 2023). "In addition to revealing a distinct cellular phenotype characteristic of cancer cells together with the underlying molecular mechanism, our results uncover an unexpected role of TFEB in regulating PtdIns3Ps levels on endosomes." (PMID 36709383, 2023). "Aberrant expressions of HPA and TFEB are associated with several human cancers." (PMID 35970822, 2022).
cancer (continued). "In cancers driven by TFEB/TFE3/MITF, expression of genes encoding endolysosomal cation channels, TRPML1, TRPML2 and TPC2, is elevated, and either the knockdown or pharmacological inhibition of these channels attenuates the growth and invasiveness of the tumors." (PMID 35406743, 2022). "Interestingly, multiple types of human cancers exhibit higher TFEB activity, which is associated with multidrug resistance, an aggressive phenotype, and poor prognosis." (PMID 35053335, 2022). "Indeed, altered TFEB expression is associated with initiation and progression of multiple types of cancer, including lung and pancreatic cancers." (PMID 30400219, 2018). "TFE3- and TFEB-associated cancers are generally considered difficult to treat through chemotherapy or irradiation, which may be related to the activation of survival factors, similar to MiTF." (PMID 26872381, 2016). "Another important finding is that TFEB should be considered as a pharmacological target, since this transcription factor may be used as an autophagy regulator due to its specific effect on molecular pathogenetic processes causing PD and cancer." (PMID 38612708, 2024). "Overall, we uncover an additional layer of TFEB regulation consisting in modulating its transcription via EGR1 and propose that interfering with the EGR1-TFEB axis may represent a therapeutic strategy to counteract constitutive TFEB activation in cancer-associated conditions." (PMID 36888606, 2023). "Cancer cells and cardiomyocytes are predisposed to oxidative stress, thus selecting pathways that ensure mitochondrial quality control, including mitophagy, and these pathological states thus provide a paradigm for understanding the cytoprotective role of TFEB‐induced activation of mitophagy." (PMID 37728021, 2023). "Moreover, TFEB-induced increases in autophagic and lysosomal activity disactivate inflammasomes and degrade the HIF1α protein, thereby halting the hypoxic response associated with cancer progression." (PMID 33912071, 2021). "Nevertheless, we can conclude that the appearance of escapers in the population of senescent cancer cells is associated with mTOR phosphorylation, however, without the transduction of signal to its substrate, which may be a cause of TFEB translocation to the nucleus." (PMID 32846959, 2020). "This paradox is mirrored in cancers characterized by constitutive TFEB and TFE3 activation, where elevated mTORC1 activity coexists with increased autophagy." (PMID 41477847, 2026). "Cancer Cell Line Encyclopedia (CCLE) data indicate that MiaPaCa-2 cells express approximately 50-fold more TFE3 mRNA than TFEB mRNA." (PMID 39869680, 2025). "A pan-cancer analysis of TFEB expression in tumors compared to normal tissue revealed a significant downregulation of TFEB in LUAD." (PMID 40083935, 2025). "Conversely, TFEB activation induced by natural compounds can trigger ferroptosis by degrading negative regulators of ferroptosis in cancer cells." (PMID 40083935, 2025). "It has been recently reported that, in cancer cells, TFEB lactylation prevents its ubiquitination and proteasome degradation, resulting in increased TFEB activity and autophagy flux." (PMID 40651947, 2025). "Next, we investigated the protein expression levels of the IL-6R/phosphorylated STAT3 (p-STAT3)/HLF/TFEB/PD-L1 axis in tissues from patients with cancer." (PMID 40779629, 2025). "For instance, several studies have demonstrated that TFEB promotes the degradation of ferritin to induce ferroptosis in cancer cells 19,20." (PMID 40083935, 2025). "Given that the function of TFEB varies across different cancer types and even among subtypes of the same cancer, we focused on the major NSCLC subtype, LUAD, which has the most extensive data available in databases." (PMID 40083935, 2025).
cancer (continued). "Extending our studies to the mammalian system, we find that TFEB knockdown alone was sufficient to drastically reduce the viability of dormant mES cells and resistant cancer cells in a diapause-like state by up to 50%." (PMID 40588651, 2025). "Thus, TFEB may be a nexus for cancer-associated metabolic stress and subsequent cell fate." (PMID 39814550, 2025). "Together, these data support that 2-DG and TFEB increase the expression of several UPR genes, whereas TFEB promotes autophagy to sustain cancer and CSC populations." (PMID 39814550, 2025). "mTOR-dependent mitochondrial translocation of TFEB suggests that the efficacy of mTOR inhibitors used in the clinic as immunosuppressant and in cancer therapy is possibly dependent on the mitochondrial activity of TFEB." (PMID 38263327, 2024). "TFEB can improve the ability of cancer cells to cope with various environmental stresses due to its ability to maintain cellular homeostasis through the regulation of autophagy." (PMID 38938061, 2024). "On the contrary, inhibiting TFEB and TFE3 activity has demonstrated beneficial effects by reducing cancer cell viability and increasing their susceptibility to anticancer therapies." (PMID 38522425, 2024). "We found that TFEB was significantly upregulated in cancer compared with that in the adjacent tissue, and the nucleus was stained as well." (PMID 38938061, 2024). "In this case, the amplification of TFEB and the evaluation of genomic stability provide new opportunities for the combination of targeted therapy and immunotherapy for this type of cancer." (PMID 38730456, 2024). "Recently, in addition to playing an important role in cancer as a key regulator of autophagy, TFEB was found to play a cancer‐promoting role in an autophagy‐independent manner; however, the mechanism remains to be explored." (PMID 38938061, 2024). "In recent years, TFEB has been proposed as a promising target for future therapies in various diseases, including cancer and CVD." (PMID 39718832, 2024). "Studies have proven that an increase in TFEB activity can improve metabolism and promote the occurrence of cancer." (PMID 38356708, 2024). "To confirm the critical role of TFEB in bacterial defense, we utilized the Cancer Cell Line Encyclopedia (CCLE) gene set, which measured whole gene expression with RNA-seq in a series of cell lines and conducted GSEA." (PMID 38711975, 2024). "This is, for example, seen in cancers harboring inactivating mutations of the phosphatase PTEN, which results in the impaired activation of TFEB." (PMID 38474423, 2024). "TFEB is not only involved in the regulation of autophagosomes but can also be used as a target for many diseases, such as cancer." (PMID 38356708, 2024). "It is generally well-accepted that TFEB is the second-most characterized member of the MiT family and is dysregulated in many cancers." (PMID 37885995, 2023). "Trans‐gnetin H significantly inhibits cancer cell viability through autophagy by suppressing the phosphorylation of TFEB and promoting its nuclear transport." (PMID 36377675, 2023). "ROS can significantly impact the quantity and quality of non-cancer cells in the vicinity, such as microglia, by modulating redox-responsive transcription factors, including TFEB, Nrf2, HSP72, and HMGB1." (PMID 38132142, 2023). "Along with autophagy‐dependent metabolic reprogramming, cancer cells uniquely exhibit the concomitance of the otherwise mutually exclusive programmes of TFEB‐driven catabolism and mTOR‐driven anabolism." (PMID 37728021, 2023). "Our data are consistent with the following model: In bladder cell lines representing high-grade cancers, TFEB localization is mostly nuclear and active thus leading to an increase in PtdIns3P levels on different endomembranes, including lysosomes." (PMID 36709383, 2023).
cancer (continued). "This review discusses how different diseases, from neurodegeneration to cancer, alter the post‐translational modification profile of TFEB, thus enabling cellular adaptation to particular pathological states." (PMID 37728021, 2023). "In this way, the post‐translational modifications of TFEB account for its otherwise paradoxical protective and deleterious effects on organismal fitness in diseases ranging from neurodegeneration to cancer." (PMID 37728021, 2023). "The findings suggest a connection between TFEB and glucose metabolism, which has significant implications for cancer prevention and enhances our understanding of the biological functions of TFEB in cancer." (PMID 37243374, 2023). "The upregulation of TFEB, a critical regulator in the autophagy-lysosomal pathway, has been connected with poor cancer prognosis." (PMID 38162504, 2023). "In vitro and in vivo studies have shown that TFEB plays an important role in metabolic diseases, immune diseases, cardiovascular diseases, cancer development, and neurodegenerative diseases." (PMID 35851059, 2022). "TFEB affects cancer progression mainly through its functions in lysosome homeostasis, metabolism, cell cycle regulation, and epithelial-mesenchymal transition." (PMID 35625599, 2022). "Positive immunoreactivity for TFEB was detected in the nuclei of both carcinoma cells and normal endometrial gland cells." (PMID 35045880, 2022). "From this analysis we identified the TFEB–lysosomal axis as the most significant pathways activated in DDCCs in vivo and in coculture, suggesting a role in the survival of disseminated cancer cells." (PMID 33670926, 2021). "Presently, there is low evidence of its involvement in cancer progression, but the expression of its downstream Ca2+ activated transcription factor, TFEB is noticeably correlated with cellular malignancy." (PMID 34572262, 2021). "Recent work shows that lysosomotropic anti‐cancer drugs promote lysosome‐mediated cancer drug resistance by stimulating activation of TFEB and the consequent increase in lysosomal biogenesis, lysosomal exocytosis, and autophagy." (PMID 34411438, 2021). "The regulatory role of mTOR and AMPK on TFEB is part of the complex metabolic scenario occurring in cancer." (PMID 33912071, 2021). "This raises a question how TRPML1 coordinates mTORC1 and TFEB to promote cancer progression if mTORC1 inhibits TFEB in cancer cells." (PMID 33419007, 2021). "TFEB expression in cancer cells showed diffuse cytoplasmic and perinuclear staining with sporadic nuclear expression." (PMID 33732651, 2021). "Taken together, these results demonstrate that TFEB-induced ITGB1 degradation can restrain the mobility of cancer cells in part via the CTSL mediated lysosomal degradation." (PMID 33803301, 2021). "In this study, we reviewed the contributions of autophagy and the lysosomal system to cancer progression and chemoresistance, and the roles of TFEB therein." (PMID 34685734, 2021). "Our data provide evidence that EphB6 is a key factor in the crosstalk between disseminated dormant cancer cells and the lung parenchyma and that the TFEB-lysosomal pathway plays an important role in the persistence of DDCCs." (PMID 33802447, 2021). "To evaluate the role of the TFEB-p21 pathway in cancer cell survival, we performed colony formation assays using cells with different levels of TFEB and p21 (WT, TFEB KO, and HeLa cells stably overexpressing TFEB-GFP), in presence or absence of doxorubicin." (PMID 32397616, 2020). "Hinokitiol activates the TFEB nuclear translocation for autophagy and lysosomal biogenesis, and induces cancer cell death." (PMID 33292395, 2020). "Given the implications of p21 in chemotherapeutic drug resistance, we evaluated the contribution of TFEB-mediated p21 upregulation in the capacity of cancer cells to survive upon the treatment doxorubicin." (PMID 32397616, 2020).